RNU6-741P (RNA, U6 small nuclear 741, pseudogene)
Gene: Small nuclear RNA gene on chromosome 15 (23,777,437 to 23,777,543, reverse strand). Ensembl gene ENSG00000206616.
Homologues: Orthologues: chimpanzee U6 (99% identical), macaque U6 (91% identical). Paralogues in human: RNU6-1251P (87% identical), RNU6-1145P (85% identical), RNU6-116P (85% identical), RNU6-16P (85% identical), RNU6-33P (85% identical), RNU6-1 (84% identical), RNU6-1060P (84% identical), RNU6-1103P (84% identical), RNU6-15P (84% identical), RNU6-2 (84% identical), RNU6-20P (84% identical), RNU6-211P (84% identical), and 1284 more.